CCR2 (C-C motif chemokine receptor 2)
Diseases named in the same sentence as CCR2 in open-access papers (continued):
Sharing a sentence is not in itself a finding about the gene and the disease.
pancreatic cancer (79 papers, 2010 to 2026). "A clinical trial (NCT01413022) involving CCR2 inhibitor PF-04136309 in association with chemotherapy was observed to be safe and tolerable for locally advanced pancreatic cancer." (PMID 38035101, 2023). "In a model for pancreatic carcinoma and liver metastasis CCR2 deficiency or CCR2 blockade has shown to impair classical monocyte recruitment, angiogenesis inhibition and relief of immunosuppression." (PMID 33262763, 2020). "Furthermore, blocking C-C motif chemokine receptor 2 (CCR2) signaling by neutrophils infiltrated in the velum interpositum region of the brain has been shown to ameliorate cachexia-associated metabolic alterations in mouse models of pancreatic cancer cachexia." (PMID 37006254, 2023). "It has been demonstrated that CCL2 and its receptor CCR2 are implicated in the development and progression of various malignancies, such as prostate cancer, breast cancer, hepatocellular cancer, lung cancer, renal cancer, pancreatic cancer, and nasopharyngeal carcinoma." (PMID 35702353, 2022). "In the pancreatic cancer model, although inhibition of CCR2 alone can reduce TAM infiltration, it leads to a compensatory accumulation of CXCR2+ TAN." (PMID 41341593, 2025). "In contrast, the CCR2 inhibitor CCX872 showed benefit over single-agent chemotherapy in combination with FOLFIRINOX in a phase Ib trial of pancreatic cancer." (PMID 41341593, 2025). "In a mouse model of pancreatic cancer, CCR2 antagonists blocked the mobilization of CCR2-positive monocytes from bone marrow into tumors, thereby limiting TAM production and curbing tumor growth and metastasis." (PMID 40083710, 2025). "Since our work focused on chemokines in the context of pancreatic cancer cells driving macrophage polarization levels, we also investigated the relative surface marker expression of two chemokine receptors, CCR2 and CCR4." (PMID 40282185, 2025). "Further underlining the suitability of our in vitro model, both pancreatic cancer cell lines showed similar modulation of the critical macrophage polarization markers arginase, CD206, and iNOS, as well as chemokine receptors CCR2 and CCR4." (PMID 40282185, 2025). "Researchers found that a significant correlation between the presence of chemokine receptor 2 (CCR2) and MDSCs in tumor tissues and the survival rates of pancreatic cancer patients has been observed in surgical specimens." (PMID 38756774, 2024). "A study tested the CCR2 antagonist CCX872-B in combination with FOLFIRINOX for patients with advanced pancreatic cancer." (PMID 38835055, 2024). "A CCR2 inhibitor, PF-04136309, was tested in combination with chemotherapy in patients with pancreatic cancer." (PMID 38835055, 2024). "Targeting the CCL2/CCR2 axis, which plays a crucial role in recruiting monocytes in various cancer types such as pancreatic cancer, offers a promising therapeutic approach to hinder the recruitment of monocytes from the bone marrow into the bloodstream." (PMID 39195299, 2024). "Blockade of the CCL2/CCR2 axis decreased tumor-infiltrating inflammatory monocytes–macrophages but increased T cell infiltration in a murine pancreatic cancer model." (PMID 38402307, 2024). "This pathway holds prognostic value in pancreatic cancer, where blocking CCR2 can rejuvenate anti-tumor immunity." (PMID 38756774, 2024). "In a phase Ib clinical trial in cases of borderline resectable and locally advanced pancreatic cancer, PF-04136309—an orally available small-molecule CCR2 inhibitor—significantly reduced bone marrow monocyte recruitment into peripheral blood." (PMID 37371612, 2023). "Two phase 1b/2 studies in patients with pancreatic cancer were launched to test the tolerability and efficacy of a CCR2 antagonist, PF-04136309." (PMID 37143666, 2023). "Under pathological conditions like osteoarthritis, pancreatic cancer, and steatohepatitis, monocytes can infiltrate target tissues by expressing the C-C chemokine receptor type 2 (CCR2)." (PMID 37388737, 2023).
pancreatic cancer (continued). "Currently, although numerous studies have confirmed the cancer promoting role of CCR2 in multiple tumors, its role in pancreatic cancer progression is not well understood." (PMID 36497150, 2022). "A phase 1b trial targeting TAMs with a CCR2 inhibitor (PF-04136309) in combination with FOLFIRINOX in patients with stage III pancreatic cancer reported a promising, high objective tumor response rate." (PMID 35404390, 2022). "We found an abnormally high expression of CCR2 in pancreatic cancer progression by bioinformatics database analysis." (PMID 36497150, 2022). "A phase I study evaluated the CCR2 inhibitor PF‐04136309 in combination with FOLFIRINOX for the treatment of patients with advanced pancreatic cancer (NCT01413022)." (PMID 35702353, 2022). "In a phase 1 trial, the administration of a CCR2 inhibitor (PF-04136309) was well tolerated and showed promising anti-tumor activity in patients with advanced pancreatic cancer." (PMID 36045408, 2022). "Next, we examined the collected tumor tissues and adjacent tissues from 30 pancreatic cancer patients and found that CCR2 expression was significantly elevated in tumor tissues compared with adjacent tissues." (PMID 36497150, 2022). "It has been a hotspot in inflammation-related diseases research, such as research on pancreatic cancer, liver cancer, and prostate cancer, and CCR2 antagonist can effectively alleviate the related diseases mediated by CCR2." (PMID 36499169, 2022). "In pancreatic cancer, CCR2 antagonists alone or combined with chemotherapeutic agents can control local tumours and are well tolerated in patients." (PMID 34464477, 2021). "CCR2 is currently a therapeutic target of interest, with promising results in clinical trials of CCR2 pharmacologic inhibitors in the treatment of pancreatic cancer and diabetes." (PMID 33888841, 2021). "Another study demonstrated that the combination therapy of CCR2 inhibition and Folfirnox improved the outcome of pancreatic cancer in patients." (PMID 34580284, 2021). "Previous studies have also demonstrated the translational potential of CCL2/CCR2 in hepatocellular carcinoma, pancreatic cancer and esophageal squamous cell carcinoma." (PMID 34745969, 2021). "PF‐04136309 is a CCR2 inhibitor that exhibited anti‐tumour activity in an orthotopic model of murine pancreatic cancer." (PMID 34464477, 2021). "Oral administration of the CCR2 inhibitor, PF‐04136309, in a preclinical pancreatic cancer model reduced the number of tumor‐infiltrating macrophages and inflammatory monocytes." (PMID 33463063, 2021). "A handful of inhibitors that selectively target CCL2/CCR2 signaling have completed Phase I clinical trials in pancreatic cancer." (PMID 34201127, 2021). "This is the case of the CCL2/CCR2 axis, which plays a role in the recruitment of monocytes in tumors: the CCR2 antagonist (PF-04136309) enhanced anti-tumor immunity, decreased tumor growth, and reduced metastasis in an orthotropic model of pancreatic cancer." (PMID 34209309, 2021). "In mice, CCR2 blockade prevents macrophage recruitment into the primary pancreatic tumor and pre-metastatic liver, and results in enhanced anti-tumor immunity, decreased tumor growth, and reduced metastasis." (PMID 34201127, 2021). "CCR2 deletion attenuated cachexia and prevented neutrophils from infiltrating the VI during pancreatic cancer cachexia." (PMID 34439145, 2021). "A phase Ib study (NCT02732938) evaluated the effect, safety and tolerability of CCR2 inhibitor PF-04136309 plus nab-paclitaxel and gemcitabine in aggressive pancreatic cancer." (PMID 33414786, 2020). "In murine pancreatic cancer models, CCR2 antagonist combined with anti–PD-1 decreased tumor burden by blocking monocyte/macrophage recruitment and relieving suppression of the CD8+ T cells." (PMID 33414786, 2020).
pancreatic cancer (continued). "Consistent with this, ongoing clinical trials have reported encouraging results of CCR2 inhibitors, especially as combination therapies, in patients with pancreatic cancers, hepatocellular carcinomas and ovarian cancers." (PMID 33322474, 2020). "For example, CSF-1R or CCR2 inhibition resulted in altered infiltration of myeloid cells by affecting CD11b+ Ly6G- Ly6Cl+ MHCII+ F4/80+ macrophages in murine pancreatic cancer models." (PMID 31878087, 2019). "The CCL2/CCR2 axis has prognostic significance in pancreatic cancer and was suggested as an effective immunotherapeutic target for a novel CCR2 inhibitor (PF-04136309)." (PMID 30925924, 2019). "In a mouse pancreatic cancer model, CCR2+ monocytes from bone marrow are blocked to mobilize into tumor by PF-04136309, a CCR2 antagonist." (PMID 31629410, 2019). "In primary tumors developed by orthotopically injected pancreatic cancer cells, reduced macrophage accumulation by a CCR2 antagonist (PF-04136309) enhances the efficacy of gemcitabine in suppressing the tumor growth." (PMID 30483271, 2018). "In a mouse model of pancreatic cancer, CCR2 inhibitors depleted inflammatory monocytes and macrophages, which resulted in decreased tumor growth and reduced metastasis." (PMID 28821810, 2017). "So in the hypoxia microenvironment of pancreatic cancer, blocking CCR2/CCR4 will likely have the potential to reduce the inflammation of pancreatic cancer tissue and fibrosis." (PMID 27271610, 2016). "The CCL2/CCR2 axis plays an important role in monocyte recruitment in many cancer types, including pancreatic cancer." (PMID 27191744, 2016). "A CCR2 antagonist (PF-04136309) also suppresses macrophage accumulation in the primary tumor developed by orthotopically injected pancreatic cancer cells, which enhances the effects of gemcitabine on the tumor growth." (PMID 26275794, 2015). "Experimental evidence found that pancreatic cancer cell-derived exosomes enriched with GOT1 inhibited cellular ferroptosis to promoted pancreatic cancer cell progression through mechanisms like upregulating CCR2 expression and activating the Nrf1/HO2559-1 pathway." (PMID 39777342, 2024). "Certainly other chemokine/receptor interactions can also contribute to immunotherapy response in pancreatic cancer, as evident from recent CCR2 and CCR5 inhibitors, which may be of interest for future study." (PMID 36881480, 2023). "Furthermore, it has been reported that monocyte mobilization via the CCL2/CCR2 axis decreases survival in pancreatic cancer." (PMID 37371612, 2023). "Furthermore, the expression of CCR2 was upregulated in pancreatic cancer cell lines AsPC1, BxPC-3, PANC-1 and SW1990 compared with normal human pancreatic ductal epithelial cell line HPDE." (PMID 36497150, 2022). "Moreover, a phase 1b study is performed for evaluating safety and efficacy of CCR2 antagonist CCX872 in patients with pancreatic cancer." (PMID 35672862, 2022). "Therefore, investigating the role and possible mechanisms of CCR2 in pancreatic cancer progression will be of great importance to unearth new therapies against pancreatic cancer." (PMID 36497150, 2022). "Several works have focused on the therapeutic activity of CCR2 inhibitors on pancreatic cancers." (PMID 34575965, 2021). "Moreover, small molecule inhibitors against CCL2 cognate receptor CCR2 are in clinical trials mainly in pancreatic cancers." (PMID 32455851, 2020). "Better results were obtained in combination regimens with the CCR2 inhibitor PF-04136309 and FOLFIRINOX chemotherapy (leucovorin, fluorouracil, irinotecan, oxaliplatin) in advanced pancreatic cancer, where reduced numbers of both circulating and intratumoral CCR2+ monocytes were measured." (PMID 32708142, 2020). "Inhibition of CCR2 and M-CSF in pancreatic cancer decreases the numbers of macrophages and CSCs." (PMID 30310855, 2018).
pancreatic cancer (continued). "Consistent with this pre-clinical study, a recent clinical trial indicates that treatment of pancreatic cancer patients with a CCR2 antagonist (CCX872) in combination with FOLFIRINOX regimen (i.e., a combination of five chemotherapy agents) improve overall survival." (PMID 30483271, 2018). "Targeting CCR2 could decreased tumor-initiating cells, relieves immunosuppression and improves chemotherapeutic effect in mice pancreatic cancer." (PMID 26992207, 2016). "Since we were also interested in the surface marker expression profiles of chemokine receptors CCR2 and CCR4, the expression of both was also measured using multicolor flow cytometry and found to associate moderately and strongly with pancreatic cancer ET ratios for CCR2 and CCR4, respectively." (PMID 40282185, 2025). "Interestingly, previous studies reported that that disrupting myeloid cell recruitment by jointly blocking CXCR2 and CCR2 could enhance anti-tumor immunity and therapeutic responses in pancreatic cancer models." (PMID 38750114, 2024). "Moreover, CCR2 antagonism decreased MDSC counts in pancreatic cancer patients (NCT02345408)." (PMID 35211124, 2022). "Our analysis of CCR2 and CCR4 revealed their differential modulation upon macrophage polarization and pancreatic cancer cell coculture." (PMID 40282185, 2025). "Research has shown that pancreatic cancer cells recruit and reprogram macrophages through the CCL2/CCR2 signaling pathway, leading to the subsequent release of TWEAK via the CCL5/TRAF6/NF-κB pathway." (PMID 39972459, 2025). "Human pancreatic cancer tumors produce CCL2, which attracts immunosuppressive CCR2+ monocytes that infiltrate the tumor microenvironment and differentiate into TAMs." (PMID 40243455, 2025). "Utilizing a CCR2 blocker, PF-04136309, within an orthotopic mouse model of pancreatic cancer demonstrated the ability to decelerate tumor growth and metastasis by diminishing MDSC infiltration in tumor tissues via the CCL2/CCR2 pathway." (PMID 38756774, 2024). "Dual targeting of CCR2 and CXCR2 improves antitumor immunity and FOLFIRINOX response in pancreatic cancer compared with either strategy alone." (PMID 37173915, 2023). "When compared to chemotherapy alone, a CCR2 antagonist, CCX827 (NCT02345408), coupled with a chemotherapeutic drugs, FOLFIRINOX, improved patients’ overall survival in advanced pancreatic cancer." (PMID 38035101, 2023). "The results of online bioinformatics database analysis indicated that CCR2 was a potential binding protein of GOT1 and is highly expressed in pancreatic cancer tissues." (PMID 36497150, 2022). "A phase 1b trial demonstrates that the orally administered CCR2 inhibitor PF-04136309 in combination with FOLFIRINOX chemotherapy is safe and tolerable for borderline resectable and locally advanced pancreatic cancer." (PMID 35672862, 2022). "Furthermore, mechanistic studies revealed that exosomal GOT1 suppressed pancreatic cancer cell iron death and accelerated pancreatic cancer progression by activating the Nrf2/HO-1 axis via upregulation of CCR2 expression, and our study may provide a new reference for pancreatic cancer treatment." (PMID 36497150, 2022). "A phase I/II trial (NCT03767582) is investigating the safety of nivolumab in combination with BMS-813160 (a CCR2/CCR5 dual antagonist) and GVAX (pancreatic cancer vaccine) in locally advanced pancreatic cancer patients." (PMID 33546207, 2021). "Another combination therapy, investigated in ongoing Phase Ib/II clinical trials, consists in the use of a dual CCR2/CCR5 antagonist plus chemotherapy or nivolumab in patients with metastatic colorectal and pancreatic cancer." (PMID 31878087, 2019). "In contrast, CCR2 inhibition attenuates the mobilization and thus leads to forming an anti-tumoral immune environment in KCKO pancreatic carcinoma and MC38 colorectal carcinoma." (PMID 31474975, 2019).
pancreatic cancer (continued). "In pancreatic cancer, inhibition of macrophage recruitment by targeting either the CSF-1 receptor (CSF-1R) (PLX6134, PLX3397) or CCR-2 (PF-04136309) resulted in a significant reduction of pancreatic cancer cells expressing high levels of the CSC marker ALDH." (PMID 27191744, 2016). "We measured CCR2, CCR5, CCR6, and CCR7, on DCs before and after surgical removal of the pancreatic tumor mass." (PMID 20976171, 2010). "Targeting this signaling axis via CCR2 blockade or CCL2-neutralizing antibodies has been shown to slow tumor progression and shunt TAMs from the TME in several preclinical tumor models, including pancreatic cancer in vivo." (PMID 40282185, 2025). "For instance, CCR2/CCR5 inhibitors, such as PF-04136309 in pancreatic cancer, could disrupt TAM/Treg recruitment in ESCA, while CXCL8/CXCR2 blockade, trialed in CRC, may reduce MDSC/NET-mediated immunosuppression." (PMID 40134607, 2025). "Furthermore, PF-04136309, a CCR2 inhibitor, was shown to reduce CCR-2+/CD14+ monocytes and macrophages in the pre-metastatic liver and primary pancreatic tumor." (PMID 39195299, 2024). "Studies in a pancreatic cancer model described that in the absence of CC-chemokine receptor 2 (CCR2) mice exhibit reduced anorexia and muscle atrophy." (PMID 37629186, 2023). "In 2 different clinical trials, CCR2 antagonists have been combined with chemotherapy in an attempt to overcome chemoresistance in pancreatic cancer patients, yet to our knowledge, CCR2 inhibition in concert with immune therapy has not yet been trialed in PDA." (PMID 36256464, 2022). "While the quantity of MDSCs was not measured in this study, a Phase Ib clinical trial in pancreatic cancer patients has shown that CCR2 inhibition with CCR2-specific antagonist CCX872 decreases monocytic MDSCs (NCT02345408)." (PMID 34065010, 2021). "Another CCR2 inhibitor, CCX872, was demonstrated to improve anti‐PD‐1 treatment in preclinical settings and positive results were also obtained when used in combination with the FOLFIRINOX strategy in pancreatic cancer patients." (PMID 33463063, 2021). "In another trial, the CCR2 specific antagonist CCX872 was used in combination with FOLFIRINOX to treat subjects with locally advanced or metastatic non-resectable pancreatic cancer." (PMID 34201127, 2021). "A phase I trial of CCR2 antagonist CCX872 plus chemotherapy FOLFIRINOX has been evaluated in non-resectable pancreatic cancer patients (NCT02345408)." (PMID 33414786, 2020). "A phase 1b trial in non-metastatic pancreatic cancer patients suggests that CCR2 inhibition decreases tumor-infiltrating macrophages and regulatory T cells, while also increasing effector T cells." (PMID 33247183, 2020). "Moreover, a phase 1b trial found that the CCR2 antagonist in combination with the FOLFIRINOX chemotherapy was safe and tolerable in the treatment of pancreatic cancer, which resulted in an endogenous anti-tumor environment." (PMID 31024838, 2019). "It is also reported that treatment with a CCR2 antagonist in combination with anti-PD1 antibody suppresses tumor growth in a mouse model of pancreatic cancer, whereas single treatment with anti-PD1 antibody is not effective." (PMID 30483271, 2018). "Most recently, Chemocentryx initiated a phase Ib trial of their next-generation CCR2 antagonist (CCX872) for non-resectable pancreatic cancer (ClinicalTrials.gov ID: NCT02345408)." (PMID 26275794, 2015). "The CCR2 inhibitor PF-04136309 has been shown to improve the survival of pancreatic cancer patients in combination with FOLFIRINOX, improves the chances of survival for individuals diagnosed with pancreatic cancer, demonstrating an improved antitumor response (NCT01413022)." (PMID 38717677, 2024). "Notably, a phase 1 trial with a CCR2 antagonist in non-metastatic pancreatic cancer patients demonstrated that CCR2 inhibition decreases the number of tumor-infiltrating Tregs." (PMID 34804061, 2021).